IRF3 (interferon regulatory factor 3)
Diseases named in the same sentence as IRF3 in open-access papers (continued):
Sharing a sentence is not in itself a finding about the gene and the disease.
infection (continued). "Marc-145 cells were pretreated with okadaic acid, and cells were then inoculated with SeV, which can activate IRF3 during the course of infection." (PMID 31618847, 2019). "Infection of wild-type and interferon-defective IRF3-/--IRF7-/- or IFNAR-/- mice with sfRNA defective WNV strains demonstrated that sfRNA production is critical to sustain infection in animals with intact interferon response." (PMID 30646609, 2019). "The different time points at which IRF3 is phosphorylated during attenuated versus virulent strains suggest that a faster transition between activated STING and phosphorylated IRF3 occurs during virulent strain infection." (PMID 30918080, 2019). "(F) Immunoflorescent staining of IRF3 in mock-infected (bottom) or HSV-1 infected (top) cells at 5 hr post infection." (PMID 31090537, 2019). "Infection of RNA viruses or their production of RNA intermediates can activate a subset of ISGs through activation of IRF3, IRF7 and NF-κB." (PMID 30952992, 2019). "The exogenous YAP1/IRF3 complex was more easily detected in HEK293 cells 6 h after infection with VSV." (PMID 31139191, 2019). "Infection recognition occurs very rapidly in monocytes and fibroblasts, leading to the activation of the transcription factors IRF3 and NF-κB, and to the implementation of the IFN transcriptional program within 4–8 h." (PMID 30949159, 2019). "This action resulted in a lower expression of IRF3, and less dimer formation, enabling a persistent infection." (PMID 31178872, 2019). "Previous characterization of the innate immune response to infection with HCMV has described important roles for IRF3-terminal, dsDNA-specific PRRs (35, 37, –, 40)." (PMID 30755509, 2019). "SINV infected IRF3−/− mice developed persistent neurological defects and spinal cord inflammation but survived infection." (PMID 30909385, 2019). "One of these mutants, VSV-∆M51-GFP31, caused a readily measurable response upon infection of HAP1 wild type cells, as shown by phosphorylation of IRF3 and STAT1 transcription factors." (PMID 31320712, 2019). "During the resting state and early phase of grass carp reovirus (GCRV) infection, synthesis and phosphorylation of IRF3/7, and mRNA levels and promoter activities of IFNs and NF-κBs are inhibited, at a time when grass carp LGP2 is overexpressed." (PMID 31080451, 2019). "IRF3 phosphorylation, measured following infection, occurred at earlier time points and to a greater magnitude in TM-treated cells as compared with control." (PMID 31467282, 2019). "MDA5 signaling pathways and innate immune cytokine (NF-κB and IRF3) were induced after IBV-M41 strain infection." (PMID 31736754, 2019). "In contrast, STING phosphorylation is triggered as early as 1 h after NH/P68 infection and leads to the phosphorylation of IRF3, a transcription factor regulating IFN-β synthesis." (PMID 30918080, 2019). "p-IRF3 was also detected in the chromatin fraction (P3) of NH/P68-infected cells, suggesting that at 8 h after NH/P68 infection, functional p-IRF3 binds to chromatin, possibly acting as transcription factor for IFN-β." (PMID 30918080, 2019). "But, in presence of amlexanox which prevented cellular TBK expression, STING and TICAM2 were phosphorylated in infection, but IRF3 phosphorylation was inhibited." (PMID 30770800, 2019). "(a, b) Susceptibility of Dgcr8-/-, Dicer-/- and parental cells to TMEV infection after inhibition of IRF3 (BX795) (a) and Nf-κB (BMS345541) (b), normalized to mock-treated cells." (PMID 31012846, 2019). "(I) Immunoflorescent staining of IRF3 in mock-infected (bottom) or ΔICP0-infected (top) cells at 5 hr post infection." (PMID 31090537, 2019). "Studies in cell culture revealed RIGI and downstream IRF3 activation occurs early in infection and subsequently controlled by HCV NS3/4A later in infection." (PMID 31374104, 2019).
infection (continued). "As an immune-evasion gene encoded by BHV-1 that promotes productive infection, BICP0 reduces IFN-β promoter activity by causing the degradation of IRF3 in transient transfection studies." (PMID 31969874, 2019). "In infected cells, however, p-STING levels were significantly reduced, particularly after WR infection, and this correlated with a reduction in p-IRF-3." (PMID 29491158, 2018). "We found that TBK1 silencing significantly decreased TBK1, p-TBK-1, and p-IRF3 expression in M. bovis infected J774a.1 cells at both 24 and 48 h post-infection." (PMID 30042930, 2018). "To see if infection-activated membrane synthesis is important for the cellular recognition of infection, we monitored phosphorylation of IRF3, degradation of Iκβ, and phosphorylation of eIF2α." (PMID 30148882, 2018). "Overall, these data suggest that zebrafish TBK1_tv1 and TBK1_tv2 associate with TBK1 and IRF3 to disrupt TBK1-IRF3 interaction under physiological conditions and SVCV infection." (PMID 29441066, 2018). "As a positive control, silencing of IRF3 resulted in reduced interferon-β expression upon hMPV infection." (PMID 29343779, 2018). "While RIG-I KO cells expressing NLS-RIG-I showed substantial IRF3 nuclear translocation upon PAfsΔNS1 infection, ablation of MAVS abolished NLS-RIG-I-mediated IRF3 activation in RIG-I-MAVS DKO cells." (PMID 30097581, 2018). "vv811 infection reduced the levels of IRF-3 activation observed after DNA transfection compared to mock-infected cells, and this was statistically significant." (PMID 29491158, 2018). "Concomitantly, miR-576-3p transcription is also activated by the transcription factor IRF3 and the miRNA accumulation increases until peak 6 h post-infection." (PMID 29813068, 2018). "Poly(I:C) is a synthetic double-stranded RNA virus, it has been previously reported that infection with poly(I:C) activates IRF3 and NF-κB to produce type I interferon." (PMID 30469505, 2018). "On the other hand, however, this stoichiometric mechanism requires NSs to accumulate to levels that are sufficient for sequestering the cellular pool of IRF3, which, during the early phase of infection, outnumbers NSs." (PMID 30232186, 2018). "Irf3 mRNA expression was decreased in microglia following infection and remained unchanged in astrocytes, contrasting with upregulation of Irf7 mRNA in both cell types between days 3 to 5 p.i. and downregulation thereafter." (PMID 29491163, 2018). "Although PAfsΔNS1 exhibited confined vRNA to the nucleus, it elicited comparable levels of IRF3 activation to that of ΔNS1-ms infection." (PMID 30097581, 2018). "It was found that IRF3 and NF-κB P65 were activated at 2 h and 4 h p.i; however, the activation of IRF3 and NF-κB P65 gradually reduced as the infection continued." (PMID 30194441, 2018). "A46 is expressed early during infection and binds to adaptor molecules downstream of Toll-like receptors (TLRs) and therefore inhibits the activation of downstream NF-κB, IRF3 and MAPK pathways." (PMID 29495547, 2018). "Although no greater RIG-I upregulation was observed in infected cells during a single-cycle or prolonged infection, PAfsΔNS1 stimulated IRF3 nuclear translocation as efficiently as ΔNS1-ms." (PMID 30097581, 2018). "NP also counteracts the host-cell type I interferon (IFN-I) response to infection by blocking the activation of interferon regulatory factor 3 (IRF3) through the retinoic acid inducible gene-I (RIG-I) and mitochondrial antiviral signaling (MAVS) pathway." (PMID 29462184, 2018). "For IRF-3, activation by RV occurred at 2 h post infection and significant suppression was also observed in FP-treated mice." (PMID 29884817, 2018). "Either pool of RIG-I by itself mediated a delayed activation of IRF3 during a single-cycle infection, suggesting a coordinated contribution by both the cytoplasmic and nuclear RIG-I to IAV sensing." (PMID 30097581, 2018).
infection (continued). "SCRV treatment increased TNFα, IL1β, and IL8 expression at 12 h post-infection in the IRF3 knockdown cells as compared with the control cells." (PMID 29755465, 2018). "In PMA-differentiated THP-1 cells, MVA infection was sufficient to trigger IRF-3 activation, and this activation required cGAS and STING." (PMID 29491158, 2018). "After SVCV infection, however, most of the individual gene differential expressions were reduced except for irf3 and nklysin." (PMID 28243233, 2017). "Our data suggested that genes under the regulatory power of IRF-3 were expressed higher in HRSV infection than EBOV Makona or Ecran infection of A549 cells." (PMID 28240256, 2017). "This places IRF3 as a critical obstacle, which most viruses must overcome to establish a persistent infection within the host." (PMID 28883463, 2017). "ISVP infection results in the faster formation of viral factories, thereby promoting a faster and more efficient sequestration of IRF3 giving ISVPs a replication advantage compared to virions." (PMID 28883463, 2017). "First, we investigated the expression patterns of IFNs, NF-κBs, and IRF3/7 in mock cells (empty vector transfected cells) post-GCRV infection." (PMID 28396670, 2017). "Before infection, all of the genes in the sGS except irf3 were upregulated in skin/fins of adult rag1−/− with nklysin and cd8 being the most upregulated." (PMID 28243233, 2017). "By responding to DNA sensors and cyclic dinucleotides, STING induces IRF3- and NF-κB –dependent pathways to elicit proinflammatory responses against infection and cancer progression." (PMID 28596706, 2017). "A549 cells expressing IRF3-GFP display similar sequestration of the transcription factor into VFs upon infection with the MRV type 1 Lang (T1L) strain." (PMID 28883463, 2017). "Immunofluorescence (IF) microscopy showed that IRF3 translocated from cytoplasm to the nucleus at 24 h post-infection in J774A.1 cells." (PMID 28529930, 2017). "We determined that ISVP infection fully blocks nuclear translocation of IRF3 strongly interfering with the production of both type I (IFNβ1) and III (IFNλ2/3) interferons." (PMID 28883463, 2017). "The results showed that the levels of all the mRNA, including those associated with IPS-1, IRF-3, IFNβ, PKR, OAS, Mx1, and MHC class I were upregulated at 24 and 48 h after infection compared to at 2 h after infection." (PMID 28194372, 2017). "Peculiarly, while TOSV NSs efficiently inhibited IRF3 activation and IFN induction when expressed via transfection or from a recombinant RVFV, infection with the parental Italian TOSV isolate resulted in IRF3 activation, IFN-β induction and Mx expression." (PMID 27338447, 2016). "Immunofluorescence confirmed that IRF3 was activated, as it was translocated to the nucleus after infection." (PMID 27538435, 2016). "The DNA-dependent activator of interferon (IFN)-regulatory factors (DAI), activated interferon regulatory factor 3 (IRF3) upon infection with HCMV and its constitutive overexpression inhibited virus replication." (PMID 26830977, 2016). "Altogether, these results clearly suggest infection-induced MST1/2 interaction-dependent activation of IRF3." (PMID 27883091, 2016). "A recently published study has shown that the FCV non-structure protein p39 (family of putative viral helicases) suppresses the IFN-β production by preventing IRF3 activation after infection." (PMID 27294868, 2016). "Mosquito-mediated infection of IRF3/7-/- mice with CHIKV also resulted in joint swelling, an arthritic manifestation often seen in symptomatic human CHIKV infections." (PMID 27760560, 2016). "We determined that by 8 hours post-infection in A549 cells and 6 hours post-infection in MEFs, IRF3 was maximally phosphorylated in response to IIV-6 infection." (PMID 27824940, 2016). "Phosphorylated and total levels of STAT1 and IRF3 were quantitated at 24 hours post-infection by immunoblot." (PMID 27505057, 2016).
infection (continued). "The phosphorylation of TANK-binding kinase (TBK1) and IRF3 was further increased in MDP-treated HCMV-infected cells compared to their levels in infection alone (lanes 3&4)." (PMID 26830977, 2016). "A previous study reported that TLR3-primed infection up-regulated the expression of IRF3 in mouse MSCs42." (PMID 27444640, 2016). "More importantly, the silencing of SNRNP200 in MDM decreases the induction of IFIH1 and IFIT1, and completely blocks IRF3 Ser386 phosphorylation within 3 hours post-infection." (PMID 27454487, 2016). "Phosphorylation in the C-terminal phosphor-acceptor has been reported to facilitate IRF3 proteasomal degradation after infection with SeV." (PMID 25763818, 2015). "All of these gene products were substantially induced late during C. muridarum infection; however, there was only a mild induction of the IRF3 gene, mimicking the early infection results." (PMID 25798928, 2015). "IRF3 normally shuttles between nucleus and cytoplasm, but is present dominantly in the cytoplasm prior infection." (PMID 25763818, 2015). "The p-IκBα was detected at 30 minutes post-infection, while the p-IRF3 was detected twelve hours post-infection." (PMID 25728279, 2015). "Several studies have demonstrated that phosphorylated IRF3 underwent ubiquitination and proteasomal degradation after infection with Sendai virus." (PMID 25763818, 2015). "Phosphorylation of IRF3 triggered by SeV-infection was greatly inhibited and the production of IFN-β was blocked when TRAF3 or TRAF6 was deleted." (PMID 26456228, 2015). "In this study, we have examined the type I interferon response and status of IRF-3 following infection of the intestinal carcinoma cell line CaCo-2 with HAstV." (PMID 25837699, 2015). "The state of activation of the IFN-I signaling pathway during persistent RSV-infection was evaluated at the level of synthesis, by initial analysis of expression of the transcription factor IRF3." (PMID 26501312, 2015). "Changes in gene expression were detected as early as 2 hours post-infection, suggesting that NFκB activation occurs much earlier than IRF3 activation, which occurred at about 36 hours post-infection." (PMID 25127040, 2014). "For the PRRSV, nsp1β, a self-cleavage product of PRRSV nsp1 during infection, was identified as the antagonist for IRF-3 activation." (PMID 25514371, 2014). "Infection of IRF3−/−/7−/− MEFs also resulted in little difference in transcript regulation between WT and A30A′ viruses and again the differences although significant, were small." (PMID 25375107, 2014). "It was well known that infection with SeV (Sendai virus) can activate IRF3 and then induce IFN-β production." (PMID 25506707, 2014). "In contrast, infection with all three of these virus strains resulted in considerable IRF3 activation under CHX treatment conditions in which virus protein synthesis was very efficiently inhibited." (PMID 24478437, 2014). "The effect of PLpro membrane localization during infection compared to the soluble form used here and its role on the IRF3 pathway is currently under investigation." (PMID 25481026, 2014). "Infection with WT or A30A′ WNVKUN viruses in WT or IRF3−/−/7−/− MEFs produced similar transcriptional profiles and showed that only a small number of genes were differentially affected between these two infections." (PMID 25375107, 2014). "After infection of WT and IRF3−/−/7−/− MEFs with WT, A30A′, or A30P WNVKUN viruses at MOI 1 total RNA was extracted 48 hpi and global gene expression was measured by microarrays." (PMID 25375107, 2014). "Infection of SK-L cells with the vGPE-/N136D and vGPE-/N136D; T830A; V2475A; A2563V, resulted in degradation of IRF3 to undetectable levels after 96 h." (PMID 24742209, 2014).
infection (continued). "Mutants 20 and 21 behaved similarly; their infection led to partial activation of IRF3, expression of ISGs (MxA and ISG56), and activation of Akt (a consequence of NS1-dependent activation of PI3K), but neither of these mutants induced apoptosis significantly." (PMID 24574395, 2014). "Recently we reported that infection with JUNV, both the pathogenic Romero and live-attenuated Candid#1 vaccine strains, activated the RIG-I/IRF3 signaling pathway as well as IFN-type I signaling in A549 cells." (PMID 24918927, 2014). "Pre-incubation of IRF-3/7−/− MEFs with increasing concentrations of exogenous IFN-α followed by infection with FL-IRAΔCS3 and FLSDX viruses demonstrated a significantly higher sensitivity of the sfRNA-deficient mutant to the anti-viral activity of IFN-α." (PMID 24473339, 2014). "This is supported by the observation that the activation of IRF3 in JEV infection is further enhanced by knockdown of TRIM21 in CHME3 cells prior to infection." (PMID 24485101, 2014). "Our transcriptome analysis of WT and IRF3−/−/7−/− MEFs upon infection with WT and PRF-deficient viruses (A30A′ and A30P) provided a detailed overview of host gene expression changes after infection and a guide for future investigations." (PMID 25375107, 2014). "Upon vesicular stomatitis virus (VSV) infection, IRF-3 and IRF-7 are modified by SUMO1, SUMO2, and SUMO3." (PMID 25514371, 2014). "In vivo experiments confirmed these results by comparing infection of wild-type C57BL/6 mice with IRF-3/7−/− mice." (PMID 24473339, 2014). "The titers of viruses accumulated in the supernatant of infected cells at this time point indicated that A30P and A30A′ viruses reached lower titers than WT virus during infection of WT MEFs but titers of all viruses in IRF3−/−/7−/− MEFs were similar." (PMID 25375107, 2014). "At 3 h, 6 h, 9 h, and 12 h post-infection, cell extracts were collected, and then analyzed IRF3 activation by detecting phosphorylated form of IRF3 using immunoblotting." (PMID 23650567, 2013). "After infection all immune response genes tested were upregulated and the transcription factors, c-Jun, IRF-3 and p50, were also increased compared to sham-infected controls." (PMID 24252391, 2013). "All four immune response genes tested were upregulated following infection as were transcription factors c-Jun, p50 and IRF-3." (PMID 24252391, 2013). "Nuclear abundance of IRF-3, p65 and p50 (the NF-κB family members activated by hMPV infection of airway epithelial cells) was then investigated by Western blot analysis." (PMID 23626834, 2013). "To further confirm that MDA5 participates in the EV71 RNA-mediated IRF3 activation upon infection, we evaluated IRF3 phosphorylation in HeLa cells that were overexpressing FLAG-tagged MDA5 protein." (PMID 23650567, 2013). "In our study, we also demonstrate increased IRF-3 production after infection with all isolates of LPAIV tested." (PMID 24252391, 2013). "We also analyzed serum cytokine production in wild type and Irf3−/− mice on days 2 and 3 post-infection." (PMID 22911267, 2012). "We also used immunofluorescence to quantify nuclear translocation of IRF3 at six hours post-infection." (PMID 22911767, 2012). "Together, the data suggest a burst in the production of inflammatory cytokines occurred between days 2 and 3 post-infection for Irf3−/− mice." (PMID 22911267, 2012). "Towards this end, we isolated bone marrow derived macrophages (BMDMs) from wild type, Irf3−/− and Ifnar−/− mice and performed a gentamicin protection assay to enumerate intracellular bacteria following infection." (PMID 22911267, 2012). "All mice harbored mild lesions on day 2 post-infection, and in the liver of Irf3−/− mice there were increased inflammatory foci, many of which contained dying cells while in wild type mice small neutrophilic foci formed that typically contained intact cells." (PMID 22911267, 2012).